HTT (huntingtin)
Diseases named in the same sentence as HTT in open-access papers (continued):
Sharing a sentence is not in itself a finding about the gene and the disease.
Cognitive impairment (34 papers, 2011 to 2025). Abnormal cognition is characterized by deficits in thinking, reasoning, or remembering. "HD is characterized by movement disorders and cognitive impairments, with its pathogenesis linked to toxic, polyglutamine (polyQ)-expanded mutant huntingtin fragments (mHTT)." (PMID 39449505, 2024). "Caused by mutations of the Huntingtin (Htt) gene, HD leads to motor impairment such as involuntary movements, cognitive impairment such as dementia, and psychiatric symptoms among which anxiety and depression are common." (PMID 34698120, 2021). "The product of the mutated gene is misfolded huntingtin protein that forms aggregates leading to impairment of neuronal function, neurodegeneration, motor abnormalities and cognitive deficits." (PMID 29435951, 2018). "A dephosphorylated state of eIF2α has been linked to cognition, which suggests that the effect of pathogenic huntingtin might also be a source of the early cognitive impairment seen in patients." (PMID 24594939, 2014). "It is an inherited disorder (mutation of the Huntingtin gene, HTT) associated with the deterioration of cortical striatal pathways and abnormal brain structure and metabolism, leading to motor and cognitive impairment." (PMID 38247879, 2024). "Huntington’s Disease (HD) is an inherited autosomal dominant neurodegenerative disorder that leads to progressive motor and cognitive impairment due to the expansion of a polyglutamine (CAG) repeat in the N-terminal region of the huntingtin (Htt) protein." (PMID 37726802, 2023). "The proteins associated with these neuroprotective effects (HTT, NEFH and NEFL) are potential drug targets for the treatment of obesity-induced cognitive impairment with semaglutide." (PMID 36998046, 2023). "The neurodegenerative Huntington’s disease (HD) is caused by a CAG-trinucleotide repeat expansion in the huntingtin gene (HTT), resulting in manifold heterogeneous motoric, psychiatric, and cognitive impairments." (PMID 34071882, 2021). "The R6/2 mouse model of HD expresses a mutant version of exon 1 HTT and develops motor and cognitive impairments, a widespread huntingtin (HTT) aggregate pathology and brain atrophy." (PMID 23593159, 2013). "The R6 mouse models of HD express a mutant version of exon 1 HTT and typically develop motor and cognitive impairments, a widespread huntingtin (HTT) aggregate pathology and brain atrophy." (PMID 24367693, 2013). "It is therefore possible that disruptions of DISC1 or HTT resulting in cognitive deficits are the result of alterations in mitochondrial function." (PMID 21298101, 2011). "A recent report found that nearly 40% of individuals who knew they carried an expanded Huntingtin allele but were not diagnosed with HD met criteria for mild cognitive impairment." (PMID 22359536, 2012). "HD is a progressive neurodegenerative disease characterized by rapid involuntary movements and cognitive impairment, ultimately leading to death, due to expansion of CAG repeats in the Huntingtin (HTT)." (PMID 36385946, 2022). "Toxic accumulation of HUNTINGTIN (HTT) aggregates in neurons bring about the aberrant phenotypes of HD, including severe motor dysfunction, dementia, and cognitive impairment at the organismal level, in an age-dependent manner." (PMID 33420088, 2021). "Formation of aggregates of mutant huntingtin (mHTT, the product of the mutant HTT gene) leads to cellular dysfunctions, and subsequent neurodegeneration which manifest clinically as motor abnormalities and cognitive deficits." (PMID 30850940, 2019).
progressive neurodegenerative disorder (25 papers, 2009 to 2026). "HD is a severe progressive neurodegenerative disorder caused by a CAG repeat expansion in exon 1 of the huntingtin (HTT) gene." (PMID 33572179, 2021). "HD is also a progressive neurodegenerative disorder with symptoms that include cognitive disturbances, mood disorders, and motor abnormalities caused by a mutation in the huntingtin (Htt) protein." (PMID 28331639, 2017). "HD is a genetic, autosomal dominant, progressive neurodegenerative disorder caused by the expansion of the CAG trinucleotide repeat found in the huntingtin gene; when the repeat number exceeds 39, individuals will develop HD within an normal lifespan." (PMID 24955833, 2014). "Huntington's disease (HD) is an inherited, autosomal dominant, and progressive neurodegenerative disorder caused by a mutation in the huntingtin gene (HTT) resulting in an abnormally long polyglutamine (CAG >40) repeat." (PMID 23847463, 2013). "This autosomal dominant and progressive neurodegenerative disorder is caused by cytosine–adenine–guanine (CAG) repeat expansions in the exon 1 of the huntingtin gene (HTT), resulting in the production of a mutant huntingtin (mHTT) protein prone to form aggregates." (PMID 35866748, 2022). "HD is an autosomal dominant, fatal, progressive neurodegenerative disorder which is monogenic with exonic CAG repeat in the huntingtin (HTT) gene." (PMID 30958120, 2019). "HD is a severe progressive neurodegenerative disorder, with a known genetic cause – additional CAG nucleotides repeats in the Huntingtin (htt) gene." (PMID 24723850, 2014).
depression (23 papers, 2010 to 2026). "Mutant huntingtin (mHTT) has been associated with several phenotypes including mood disorders and depression." (PMID 28920088, 2017). "Conversely, individuals with major depression have been shown to have elevated rates of the huntingtin disease-associated alleles (3 allele carriers in 1,000 patients,)." (PMID 21298101, 2011). "However, genetic phospho-ablation at S1181 and S1201 in the mouse showed reduction in anxiety/depression-like phenotypes and increased axonal transport of BDNF, suggesting HTT function is associated with etiology of mood disorders and anxiety/depression in HD." (PMID 41303392, 2025). "Because the transgenic mice that express mutated HTT protein have been shown to exhibit depression, such as behavior, it is possible that HTT-related signaling may be responsible for the progression of depression symptom." (PMID 35928791, 2022). "Furthermore, 10 participants with huntingtin gene mutation were diagnosed with depression and received treatment prior to this study, and the effect of drugs on their symptoms could not be assessed." (PMID 34393630, 2021). "For example, HTT, ATXN1, ATXN7, and CACNA1A were associated with neuropsychiatric disorders such as depression and schizophrenia." (PMID 41254939, 2025). "It is therefore unclear whether the overlap on the effects of disruption of DISC1 and HTT overlap within the domains of depression or schizophrenia." (PMID 21298101, 2011). "As the expression of huntingtin is modulated by its polyglutamine tract, the effect of HTT CAG repeat size variations on depression might be due to altered endogenous levels of huntingtin." (PMID 29225330, 2017). "Among GWAS genes that interacted the most with depression portrait genes were the histone acetyltransferase, EP300, the Rho GTPase, RHOA, the heat shock protein HSPA1A, the dopamine receptor, DRD2, the glutamate receptor, GRM5, the huntington gene, HTT, and the estrogen receptor, ESR2." (PMID 33589676, 2021). "Animal studies using the BACHD mouse model of HD have suggested that huntingtin lowering therapies targeting the hypothalamus may have beneficial effects on non-motor features such as metabolic dysfunction and depression." (PMID 25659157, 2015). "The aim of the present study was to assess and compare depression, anxiety and hopelessness rates in individuals with and without an abnormal expansion of CAG repeats in the huntingtin (HTT) gene and healthy controls." (PMID 34393630, 2021).
frontotemporal dementia (23 papers, 2010 to 2025). Frontotemporal dementia (FTD) comprises a group of neurodegenerative disorders, characterized by progressive changes in behavior, executive dysfunction and language impairment, as a result of degeneration of the medial prefrontal and frontoinsular cortices. "Besides it had demonstrated the presence of huntingtin‐positive aggregates mainly in the frontal cortex of frontotemporal lobar degeneration (FTLD)‐TDP43 patients with pathological expansions of the HTT gene." (PMID 38418081, 2024). "Recently, a link between the CAG repeats in the HTT gene and frontotemporal dementia/amyotrophic lateral sclero (FTD/ALS) phenotypes has been proposed." (PMID 38418081, 2024).
neuroblastoma (23 papers, 2007 to 2025). Neuroblastoma (NB) is the most common solid, extracranial childhood tumor. "The subcellular localization of this interaction was differentially modulated by mHTT in the striatum of HD mice at an early versus later stage of HD-like pathology, while loss of HTT in human neuroblastoma cells altered the subunit assembly state of Mediator." (PMID 40169779, 2025). "To this end, we perform RNAi screening in mouse neuroblastoma cells to attempt to identify novel aggregation-modifiers for mutant huntingtin (Htt), a causative protein of HD, in mammals." (PMID 24705917, 2014). "In summary, SC treatment reduces the aggregation of mutant polyQ-containing huntingtin proteins both in a C. elegans animal model and in a mouse neuroblastoma cell line." (PMID 40177520, 2025). "For these studies we used the mouse transgenic N2a neuroblastoma cell line over-expressing an ecdysone-inducible mutant Huntingtin protein with an expanded polyQ repeat (150Q) attached to EGFP (HD150Q-EGFP)." (PMID 40177520, 2025). "The significant functional enrichment of these candidates in ion homeostasis and energy production, and potentiated intracellular calcium responses we observed with genetic deletion of HTT in neuroblastoma cells, suggest they are primary sensitizing pathways." (PMID 40169779, 2025). "For example, a peptide sequence generated from CaM disrupts its binding to huntingtin reducing its cytotoxicity in differentiated neuroblastoma cells (SH‐SY5Y) and providing neuroprotection in a mouse (R6/2) model (Dudek, Dai, & Muma, 2008, 2010)." (PMID 31774219, 2020). "Next, we developed human neuroblastoma SH‐SY5Y cell lines that stably express N‐terminal mutant huntingtin." (PMID 19338577, 2010). "Mutant huntingtin overexpressing neuroblastoma cells with ubiquitin cotransfection showed increased protein aggregates and apoptic cell death, suggesting ubiquitin involvement in HD pathological cell death." (PMID 17327906, 2007). "In a transgenic mouse neuroblastoma cell line over-expressing a mutant huntingtin protein with 150 tandem glutamines, SC reduced aggregates of the polyQ-containing mutant protein by suppressing the Endoplasmic Reticulum Unfolded Protein Response (ER-UPR) triggered by aggregation." (PMID 40177520, 2025). "Moreover, expression of mutant HTT in mouse neuroblastoma and MSNs showed enhanced SOCE activation, which was reversed by RNAi knockdown of Orai1, TRPC1, or STIM1." (PMID 40169779, 2025). "In addition, transient hyperosmotic treatment of human neuroblastoma SH‐SY5Y cell lines stably expressing mutant truncated huntingtin (Q88) significantly increases the number of cells with aggregates." (PMID 31774219, 2020). "Enhanced degradation of mutant α-synuclein and huntingtin in PC12 neuroblastoma cells." (PMID 30210290, 2018). "We created neuroblastoma SH‐SY5Y cells which stably express N‐terminal mutant huntingtin and endogenously express TG 2 (SHSY5Y‐htt‐N63‐148‐Q cells) and examined the effect of AAV‐mediated expression of CaM‐peptide on TG‐activity and mutant huntingtin‐associated neurotoxicity." (PMID 19338577, 2010). "Following our previous studies in HD, in this study we aim to investigate in vitro in a neuroblastoma cellular model of HD, the effect of CYP46A1 overexpression, an essential enzyme in cholesterol metabolism, on huntingtin aggregation and levels." (PMID 32276655, 2020). "(A) Nuclear extract (NE), and cytosolic extract (CE) were purified from human neuroblastoma SH-SY5Y cells and the protein fractions were analyzed by western blots (WBs) to detect HTT, ATXN3, PNKP, and HAP1 levels in these sub-cellular fractions." (PMID 30994454, 2019). "Overexpression of miR‐196a leads to a reduction of mutant huntingtin (HTT) and the formation of pathological aggregates in HD models of human embryonic kidney cells and mouse neuroblastoma cells." (PMID 29972883, 2018).
Chorea (22 papers, 2011 to 2025). Chorea (Greek for 'dance') refers to widespread arrhythmic involuntary movements of a forcible, jerky and restless fashion. "Huntington's disease (HD) is an inherited autosomal dominant neurodegenerative disorder caused by mutation in the huntingtin (Htt) gene and characterized by progressive chorea and impaired cognitive function." (PMID 21912697, 2011). "The abnormal amplification of a CAG sequence in the HTT gene in ALS with chorea has an obvious familial genetic tendency, and most patients have a mild disease course." (PMID 36596053, 2022). "HD is the commonest inherited cause of chorea, which is caused by variably expanded CAG trinucleotide repeats in exon 1 of the huntingtin (HTT) gene on chromosome 4p16.3." (PMID 35733931, 2022). "Clinical features of HD include chorea, cognitive dysfunction, and psychiatric symptoms that are caused by excessive repeat of CAG trinucleotide in the huntingtin gene (Htt)." (PMID 31659519, 2019). "This slight motor impairment was correlated with risk age, which confirmed that the genetically induced pathological process and huntingtin abnormal functions may start before chorea appearance." (PMID 27087746, 2016).
Brain atrophy (17 papers, 2009 to 2026). Partial or complete wasting (loss) of brain tissue that was once present. "Smith and co-workers reported that CoQ10 administration resulted to exert a therapeutic benefit in a dose dependent manner in HD mice, improving motor performance and grip strength, and reducing weight loss, brain atrophy and huntingtin inclusions." (PMID 27713230, 2009). "At 11 months, BAC226Q mice showed significant reduced life span, gradual weight loss and exhibited neuropathology including significant brain atrophy specific to striatum and cortex, striatal neuronal death, widespread huntingtin inclusions, and reactive pathology." (PMID 35023827, 2022). "HD is fatal and arises from a mutation in the huntingtin (HTT) gene, which results in decreased neuronal health followed by brain atrophy, with spiny projection neurons (SPNs) of the striatum being especially vulnerable to degeneration." (PMID 42209021, 2026). "These disturbances in functional connectivity were strongly associated with selective brain atrophy and motor performance, demonstrating that regional brain connectivity measures may provide a unique window into the structural and functional consequence induced by mutant huntingtin in the brain." (PMID 29196686, 2017). "We hypothesized that everolimus would decrease mutant huntingtin levels in brain and have neuroprotective effects as measured by decreased brain atrophy." (PMID 20569486, 2010). "Moreover, TG2 deletion did not change the huntingtin aggregate load in cortex or striatum and did not decrease the brain atrophy observed in either mouse line." (PMID 24955833, 2014).
dementia (17 papers, 2013 to 2025). Loss of intellectual abilities interfering with an individual's social and occupational functions. "Important evidence supporting the association of the HTT gene with AD is the reported neuropathological study of 15 elderly HD subjects that found evidence of co‐occurring AD neuropathology in 82% of the cases with prominent dementia." (PMID 38418081, 2024). "Huntington’s Disease (HD) is a neurodegenerative disorder of the central nervous system that is distinguished by psychiatric and behavioral alterations, undesired motions, and dementia, and caused by abnormal CAG repeat expansion in exon 1 of the Huntingtin gene (HTT)." (PMID 32679881, 2020).
spinocerebellar ataxia (17 papers, 2009 to 2025). "HD, the result of a mutation in the huntingtin (HTT) gene, is the only purely genetic neurodegenerative disease, although there are other hereditary neurodegenerative diseases like spinocerebellar ataxia (SCA)." (PMID 39683859, 2024). "It was shown that pharmacological activation of autophagy reduces the levels and toxicity of mutant huntingtin, mutant proteins in spinocerebellar ataxia, mutant α-synuclein and mutant tau in either mouse or Drosophila models." (PMID 25699594, 2015). "No mutations were observed in ataxia-related genes or huntingtin (HTT) gene." (PMID 36614069, 2022). "This study involved six genes (ATXN1, ATXN3, ATXN7, HTT, NOP56, and PPP2R2B), while a higher detection rate has been reported in a spinocerebellar ataxia cohort (4.4%, 22/498), which included five genes (ATXN2, ATXN3, NOP56, AR and HTT)." (PMID 38308084, 2024). "No role for this gene has been reported so far in mutant huntingtin aggregation, but mutations in AFG3L2 cause the dominant spinocerebellar ataxia, SCA28, a neurodegenerative disorder characterized by Purkinje cell degeneration." (PMID 21915392, 2011).
Anxiety (13 papers, 2012 to 2025). Intense feelings of nervousness, tension, or panic often arise in response to interpersonal stresses. "An anxiety-like behavior is also observed in CaMKCreERT2; Httflox/flox mice, showing that a loss of function of HTT only in mature cortical and hippocampal neurons in adults is sufficient to lead to anxiety." (PMID 24795586, 2014). "In addition, the reported association of the HTT promoter polymorphism with anxiety-related traits in the general population further stimulates interest in HTT as a possible candidate gene to modify the WBS behavioral phenotype." (PMID 23972161, 2013). "We were then interested in examining the effect of inactivation of mutant HTT in SF1 neurons for the development of anxiety-like behavior in the BACHD mouse model." (PMID 25271967, 2014). "Overall, our analyses reveal that the depletion of huntingtin in mature cortical and hippocampal neurons has a significant effect on anxiety-related behavior." (PMID 24019939, 2013). "Our results show that inactivation of mutant HTT in leptin receptor-expressing neurons in the BACHD mouse using cross-breeding based on a cre-loxP system did not have an effect on the metabolic phenotype or anxiety-like behavior." (PMID 23251447, 2012).